DDX25 (DEAD-box helicase 25)
Description:
ATP-dependent RNA helicase. Required for mRNA export and translation regulation during spermatid development (By similarity).
Synonyms: GRTH
Tractability: PROTAC: ubiquitination databases record sites on it; its protein half-life has been measured.
Gene: Protein-coding gene on chromosome 11 (125,903,348 to 125,943,702, forward strand). Ensembl gene ENSG00000109832.
Subcellular location: Cytoplasm; Nucleus
Subcellular location (Human Protein Atlas): Nucleoplasm; Cytosol
Gene Ontology:
Molecular function: protein binding; ATP binding; RNA helicase activity; ATP hydrolysis activity; nucleic acid binding
Biological process: mRNA export from nucleus; regulation of translation; spermatid development
Cellular component: cytosol; chromatoid body; cytoplasm; cytoplasmic stress granule; nucleus
Genetic constraint (gnomAD): Loss-of-function variants: 70 observed, 63.37 expected, observed/expected ratio (o/e) 1.1, 90% interval 0.91 to 1.35. The upper end of that interval is the gene's LOEUF score, 1.35, which puts it in group 5 of 6, group 1 being the genes least tolerant of losing a copy. Missense variants: 587 observed, 614.02 expected, observed/expected ratio (o/e) 0.96, 90% interval 0.89 to 1.02. Synonymous variants: 211 observed, 216.04 expected, observed/expected ratio (o/e) 0.98, 90% interval 0.87 to 1.1.
Homologues: Orthologues: chimpanzee DDX25 (99% identical), macaque DDX25 (98% identical), rat Ddx25 (94% identical), dog DDX25 (93% identical), mouse Ddx25 (93% identical), pig DDX25 (93% identical), rabbit DDX25 (93% identical), guinea pig DDX25 (90% identical), tropical clawed frog ddx25 (64% identical). Paralogues in human: DDX19B (65% identical), DDX19A (64% identical), EIF4A1 (31% identical), EIF4A2 (30% identical), EIF4A3 (29% identical), DDX4 (26% identical), DDX3X (26% identical), DDX3Y (26% identical), DDX5 (25% identical), DDX6 (25% identical), DDX17 (25% identical), DDX1 (25% identical), and 26 more.
Diseases named in the same sentence as DDX25 in open-access papers:
DDX25 is named in the same sentence as 8 diseases in open-access papers, as found by Europe PMC text mining. Sharing a sentence is not in itself a finding about the gene and the disease. The quoted sentences say what the papers report.
infertile (2 papers, 2020 to 2023). "Importantly, different polymorphisms of the Ddx25 gene are reported in infertile Chinese and Japanese men, respectively." (PMID 32050598, 2020). "In another study, miR-469 was found to be up-regulated in GRTH/DDX25 null mice where it was reported to target Tnp2 and Prm2, which ultimately resulted in infertility due to failure in the generation of elongated spermatids." (PMID 37924131, 2023). "In infertile Japanese men, a missense mutation Arg242His in exon 8 was identified, which leads to the absence of the phosphorylated form of DDX25." (PMID 32050598, 2020).
breast carcinoma (1 paper, 2025). "Furthermore, the nuclear expression of DDX25 may serve as a predictive biomarker for the response to AZD4573 treatment in breast cancer." (PMID 40713627, 2025). "Taken together, the nuclear translocation of DDX25 is crucial for the resolution of T-R conflicts, which influences the sensitivity to AZD4573 in breast cancer cells." (PMID 40713627, 2025). "Considering the essential role of resolving T-R conflicts in maintaining cell viability, we propose that DDX25, the RNA helicase may serve both as a functional modulator of T-R conflicts resolution and a predictive biomarker for AZD4573 response in breast cancer." (PMID 40713627, 2025).
male infertility (1 paper, 2010). The inability of the male to effect fertilization of an ovum after a specified period of unprotected intercourse. "These functional categories contained several genes playing a role in spermatogenesis, fertilization, and determination of the testicular mass, some of which are involved in human and murine male infertility (DDX25 and FKBP6) (SPAG6)." (PMID 20576090, 2010).
Vertigo (1 paper, 2025). An abnormal sensation of spinning while the body is actually stationary. "Similarly, rs56819906 and rs73626678 (R2 = 0.52) were eQTLs for DDX25 in tibial nerve tissue and associated with vertigo, with p = 7.6 × 10−5 for GG vs. AA for rs56819906 and p = 1.8 × 10−4 for TT vs. CC for rs73626678." (PMID 40913328, 2025).
viral infection (1 paper, 2017). "Strikingly, we observed an increased production of DDX25 both in vivo and in vitro during viral infection." (PMID 28824886, 2017). "So we constructed Ddx25-Tg mice that overexpress DDX25 to identify the role of Ddx25 in virus infection in vivo." (PMID 28824886, 2017). "As such, DDX25 has additional function for viral infection in human cells and mouse models." (PMID 28824886, 2017). "The expression profile and the role of DDX25 during viral infection has not been reported yet." (PMID 28824886, 2017).
cancer (1 paper, 2019). A tumor composed of atypical neoplastic, often pleomorphic cells that invade other tissues. "While RBFOX3, RBM11 (RNA binding motif protein 11) and DDX25 (DEAD-box helicase 25) are generally downregulated in cancers compared to normal cells, the dysregulation of CELF5, ELAVL2 and ESRP1 is dependant on the type of cancer." (PMID 30704403, 2019).
infection (1 paper, 2017). The state of being infected such as from the introduction of a foreign agent such as serum, vaccine, antigenic substance or organism. "Meanwhile, the mRNA expression of Ifnα, Ifnβ, Ifnγ, Tnfα, and selective chemokines (Cxcl1, Cxcl2, and Ccl5) by leukocytes was lower in the blood of Ddx25-Tg mice on day 1 post-infection." (PMID 28824886, 2017). "While, at 48 h post-infection, the IFNβ mRNA level was increased in DDX25 overexpressed cells." (PMID 28824886, 2017).
DDX25 also shares sentences with these, for which no sentence is quoted: tumor (1 paper).